MROH7-TTC4 (MROH7-TTC4 readthrough (NMD candidate))
Synonyms: HEATR8-TTC4
Gene: Protein-coding gene on chromosome 1 (54,641,786 to 54,742,308, forward strand). Ensembl gene ENSG00000271723.
Genetic constraint (gnomAD): Missense variants: 1,534 observed, 1,684.5 expected, observed/expected ratio (o/e) 0.91, 90% interval 0.87 to 0.95. Synonymous variants: 635 observed, 676.25 expected, observed/expected ratio (o/e) 0.94, 90% interval 0.88 to 1.